PF4 (platelet factor 4)
Diseases named in the same sentence as PF4 in open-access papers (continued):
Sharing a sentence is not in itself a finding about the gene and the disease.
Splenomegaly (2 papers, 2018 to 2024). Abnormal increased size of the spleen. "In previous studies, several cytokines, such as SCF, TNF-α, PDGF, TGF-β, bFGF, PF4, and IL-8 contributed to the expansion of malignant clones from the BM to the spleen as an EMH site, leading to the development of splenomegaly in MF patients." (PMID 29562644, 2018).
uremia (2 papers, 2021 to 2025). A clinical syndrome associated with the retention of renal waste products or uremic toxins in the blood. "During dialysis, blood–film contact in uremia causes PF4 and β-thromboglobulin release from platelets due to granule–membrane defects, activating platelets." (PMID 40422573, 2025).
-dependent syndrome (1 paper, 2022). "Immune thrombotic thrombocytopenia and other PF4 dependent syndrome are likely associated with ChAdOx1 and Ad26.COV2.S adenovirus vector vaccines, mostly occurring in women usually within 4–37 days of first dose of vaccine." (PMID 35368622, 2022). "However, immune thrombotic thrombocytopenia and other PF4 dependent syndrome are likely associated with ChAdOx1 and Ad26.COV2.S adenovirus vector vaccines, mostly occurring in women usually within 4 to 37 days of first dose of vaccine." (PMID 35368622, 2022).
acute lymphoblastic leukemia (1 paper, 2012). Leukemia with an acute onset, characterized by the presence of lymphoblasts in the bone marrow and the peripheral blood. "Platelet factor 4, pro-platelet basic protein precursor, and complement component 3 are known to be diagnostic in a panel for acute lymphoblastic leukemia in children." (PMID 22538116, 2012).
alcoholic hepatitis (1 paper, 2015). Acute hepatitis resulting from ingestion of alcohol. "Indeed, Pf4 mRNA has been shown to be up-regulated in alcoholic hepatitis patients." (PMID 26519296, 2015).
and mouth disease (1 paper, 2025). "Our previous study demonstrated that PF4 inhibits the entry of enterovirus A 71 (EV71) and coxsackievirus A16 (CA16), which cause hand, foot, and mouth disease (HFMD)." (PMID 39772852, 2025).
Aortic dissection (1 paper, 2022). Aortic dissection refers to a tear in the intimal layer of the aorta causing a separation between the intima and the medial layers of the aorta. "Nine proteins (Lumican, FGL1, PI16, MMP9, FBN1, MMP2, VWF, MMRN1, and PF4) related to the pathogenesis of aortic dissection were identified by David /Ease and String techniques as candidate biomarkers for verification test." (PMID 35910577, 2022).
atrial fibrillation (1 paper, 2011). A disorder characterized by an electrocardiographic finding of a supraventricular arrhythmia characterized by the replacement of consistent P waves by rapid oscillations or fibrillatory waves that vary in size, shape and timing and are accompanied by an irregular ventricular response. "Recently, Cxcl14, also known as Pf4 (platelet factor 4), was found to be slightly elevated in the left atrium of patients with atrial fibrillation." (PMID 22039477, 2011).
autoimmune hemolytic anemia (1 paper, 2022). Autoimmune hemolytic anemia (AIHA) is an autoimmune disorder in which various types of auto-antibodies are directed against red blood cells causing their survival to be shortened and resulting in hemolytic anemia. "On presentation, two patients had concurrent active Hepatitis C and HIV viral infection, one had autoimmune hemolytic anemia (Evans syndrome), and one patient had weakly positive platelet factor 4 antibodies." (PMID 36146522, 2022).
bleeding disorders (1 paper, 2025). "The proper expression of PF4, driven by GATA1, is necessary for maintaining platelet function and preventing bleeding disorders." (PMID 40937321, 2025).
chronic fatigue syndrome (1 paper, 2024). "Long COVID exhibits similarities with myalgic encephalopathy/chronic fatigue syndrome (ME/CFS), however, so it is of interest that thrombospondin and platelet factor 4 are both raised in the plasma of individuals with ME/CFS." (PMID 39409138, 2024).
chronic hepatitis (1 paper, 2013). An active inflammatory process affecting the liver for more than six months. "Platelet sensitivity to stimuli in patients with liver cirrhosis has been demonstrated to be higher than in healthy controls and it was indicated that platelet factor 4 was activated and upregulated in chronic hepatitis and liver cirrhosis." (PMID 24223640, 2013).
chronic idiopathic myelofibrosis (1 paper, 2024). "The platelet factor 4 (PlF4) protein is associated with chronic idiopathic myelofibrosis and megakaryoblastic leukemia (AMGL)." (PMID 38418685, 2024).
chronic osteomyelitis (1 paper, 2025). "Anti-CXCL4 (PF4) antibody was found to inhibit the percentage of Tregs, while the recombinant CXCL4 protein increased the percentage of Tregs in the CD4+ T in chronic osteomyelitis." (PMID 40114921, 2025).
clear cell renal cell carcinoma (1 paper, 2024). "Multispectral immunofluorescence and immunohistochemistry identified PF4+ macrophages in clear cell renal cell carcinoma (ccRCC) and adjacent normal tissues, indicating that activate PF4+ macrophages might regulate the profibrotic and pro-tumorigenic microenvironment after renal injury." (PMID 38167034, 2024).
cleft lip (1 paper, 2021). Congenital defect in the upper lip where the maxillary prominence fails to merge with the merged medial nasal prominences. "In fact, the roles of PTX3 and PF4 in cleft lip and palate have never been reported before and we suggest this as a potential new avenue for investigation since they modulate the binding of bFGF with its receptors." (PMID 34068496, 2021).
cognitive diseases (1 paper, 2024). "Combined with other studies, PF4 is a promising molecule possibly crucial for neurodegenerative and cognitive diseases, and could be used both as a biomarker and as a therapeutic." (PMID 38485973, 2024).
coronary thrombosis (1 paper, 2022). Coagulation of blood in any of the coronary vessels. "Actually, the case is about a 69-year-old man who developed CVS thrombosis with anti-PF4 autoantibodies alongside coronary thrombosis." (PMID 35214765, 2022).
diabetes nephropathy (1 paper, 2021). "Platelet factor 4 was increased basally in T2D, as has been reported previously, and has been shown to be discriminatory for diabetes nephropathy and neuropathy." (PMID 34248840, 2021).
endotoxemia (1 paper, 2014). "However, we and some other researchers have previously demonstrated that propofol could reduce serum levels of platelet factor 4 (PF4) released from platelet and partially corrects the hypercoagulopathy associated with endotoxemia in rats." (PMID 25180066, 2014).
gram-negative bacterial infections (1 paper, 2021). Infections caused by bacteria that show up as pink (negative) when treated by the gram-staining method. "PF4 and anti-PF4/polyanion antibodies could play a physiologic role in the host immune defense, particularly against Gram-negative bacterial infections." (PMID 33578859, 2021).
hair loss (1 paper, 2020). "Our findings suggest that PF4 inhibits human hair follicle growth probably by promoting androgen receptor signaling and downregulating hair growth-promoting genes, providing thoughtful insights into the application and optimization of PRP in hair loss treatment." (PMID 32953277, 2020).
hemophilia (1 paper, 2024). Hemophilia is a genetic disorder characterized by spontaneous hemorrhage or prolonged bleeding due to factor VIII or IX deficiency. "The study revealed that patients with hemophilia have elevated baseline levels of platelet activation, indicated by increased platelet P-selectin expression and higher plasma concentrations of the soluble platelet activation markers PF4, CXCL7, and RANTES when compared to healthy controls." (PMID 38337802, 2024).
heroin addicts (1 paper, 2021). "For example, major platelet-derived immune molecules, including the chemokine PF4 and PPBP, were significantly increased at the transcription level in AW heroin addicts." (PMID 34489980, 2021).
Mks (1 paper, 2024). "Although CXCL4 (PF4) inhibits the development of Mks, PF4 is a useful marker for enriching Mks in adults." (PMID 38580775, 2024).
Onset (1 paper, 2022). The age group in which disease manifestations appear. "Thus, very high titers of anti‐PF4/H IgG antibodies likely contribute to platelet activation without heparin in SRA, similar to that previously suggested in delayed‐onset HIT patients." (PMID 35971886, 2022).
osteonecrosis (1 paper, 2011). A none disease characterized by death of bone tissue due to a lack of blood supply. "Platelet factor 4 (PF4) and growth factors in releasates, platelet lysates, platelet-poor plasma (PPP), and serum in 14 patients with osteonecrosis (ON) and in 10 controls (Ctr)." (PMID 21281264, 2011).
peritonitis (1 paper, 2023). Inflammation of the peritoneum (tissue that lines the abdominal wall and covers most of the organs in the abdomen). "The key finding of the present study is that PF4 was effective in clearing bacteria in the mouse model of peritonitis and significantly improved survival." (PMID 37868353, 2023). "Here, we investigated the effect of recombinant PF4 (rPF4) on phagocytosis of Gram-positive Staphylococcus aureus in vitro and examined its impact in a mouse model of S. aureus peritonitis." (PMID 37868353, 2023). "This suggests that phagocytosis was the primary mechanism of PF4 action in the peritonitis model." (PMID 37868353, 2023).
post-traumatic stress disorder (1 paper, 2020). An anxiety disorder precipitated by an experience of intense fear or horror while exposed to a traumatic (especially life-threatening) event. "Another module downregulated in the early adversity group was related to platelet activation and wound healing (hub genes: GP9, CMTM5, TUBB1, GNG11, PF4), and resembled a co-expression module previously found over-expressed in post-traumatic stress disorder resilient soldiers." (PMID 32066736, 2020).
psychosis (1 paper, 2024). "Interestingly, among these proteins, there were the Heparin cofactor 2, Immunoglobulin heavy constant mu, the platelet factor 4, Filamin-A and Actin, cytoplasmic 1, Thymosin beta-4 which locus maps within the deleted region of chromosome 22 and found to be strongly associated with psychosis." (PMID 38418685, 2024).
pulmonary emphysema (1 paper, 2025). A subcategory of chronic obstructive pulmonary disease (COPD). "Platelet activation can release mediators such as platelet factor 4 (PF4), which may enhance human leukocyte elastase (HLE) activity, contributing to pulmonary emphysema formation." (PMID 40028201, 2025).
sarcoma (1 paper, 2012). A usually aggressive malignant neoplasm of the soft tissue or bone. "Furthermore, PF-4var but not PF-4 is produced constitutively by smooth muscle cells and by sarcoma cells after induction with cytokines, such as IL-1β and TNF-α, indicating that the regulated expression of these two PF-4 variants is different." (PMID 22384011, 2012).
stenosis (1 paper, 2017). "However, in the present study, ROC test showed that PF4 could act as a biomarker for the diagnosis of severe CAD (triple-vessel disease with/without left main stenosis) requiring CABG procedure." (PMID 28947991, 2017).
Stillbirth (1 paper, 2019). Death of the fetus in utero after at least 22 weeks of gestation. "The CXCL8 and PF4 are located within regions associated with calving-to-conception interval or calving-to-first-estrous interval, while S100A8 is within a stillbirth QTL region." (PMID 31374089, 2019).
thrombocytopenia type 2 (1 paper, 2022). "There are also existing clinical disadvantages of LMWH, including heparin-induced thrombocytopenia type 2, an immunologic reaction in which antibodies to the heparin-platelet factor-4 complex are formed." (PMID 36297616, 2022).
thymoma (1 paper, 2015). A neoplasm arising from the epithelial cells of the thymus. "In MG patients with versus without thymoma, 58 lncRNAs had 271 ‘cis’ genes upstream or downstream of their chromosomal position: lncRNA oebiotech_22652 had the highest number of ‘cis’ genes, whereas lncRNA oebiotech_12244 had 6 ‘cis’ genes(PPBP, CXCL1, CXCL5, PF4V1, PF4, and C14orf45)." (PMID 25889429, 2015).
urothelial cell carcinoma (1 paper, 2018). "Likewise, PF4 (platelet factor 4) inhibits tumor growth and metastasis by suppressing neovascularization, consistent with the positive association we found between PF4 methylation and later urothelial cell carcinoma." (PMID 29310692, 2018).
tumor (155 papers, 2008 to 2026). "Recombinant platelet factor-4 variant chemokine CXCL4L1 was shown to significantly suppress tumor growth and metastasis by inhibiting angiogenesis." (PMID 36612163, 2022). "PF4 functions as a promotor of platelet chemotaxis into the tumor microenvironment and has been linked to carcinogenesis." (PMID 31215484, 2019). "The role of platelets in lung tumorigenesis and tumor progression has attracted much interest and has been strongly linked to tumor production of PF4." (PMID 31215484, 2019). "A variety of platelet-associated chemokines can modulate inflammation within the tumor environment and tumor angiogenesis, such as platelet factor 4 (PF-4/CXCL4) and connective tissue-activating peptide III (CTAP-III)." (PMID 30539019, 2018). "Together, our data suggest an association of decreased PF4 with increased tumor progression in the clinical setting, and provide insight for therapies aimed targeting metastasis." (PMID 27223426, 2017). "The effects of SH on tumor vessels were caused in part by its capability to restore the balance between pro-angiogenic factor (bFGF) and anti-angiogenic factor (PF4)." (PMID 25749075, 2015). "PF4 exerts pleiotropic biological effects, and our study and studies by other investigators strongly indicate that its tumor-growth-inhibitory effect is closely associated with its antiangiogenic activity." (PMID 21693026, 2011). "PF4 levels in circulation and within tumors have been associated with increased tumor growth." (PMID 37176055, 2023). "Activated platelets may then promote tumor proliferation, angiogenesis, metastasis, and cancer-associated thrombosis through the release of growth factors, such as platelet-derived growth factor, platelet factor 4, and platelet-reactive protein." (PMID 36110962, 2022). "At this point we need to clarify if after 10 days of treatment with PF4-DLR alone it is required to continue the anti-angiogenic therapy in association with ILK1 knock down or it is sufficient to continue only knocking down ILK1 to block or eradicate the tumor." (PMID 21060779, 2010). "To investigate the role of IMs in tumor immunity, we used Pf4 Cx3cr1 mice, which selectively deplete CD206hi IMs and, to a lesser extent, CD206lo IMs." (PMID 40630529, 2025). "Specifically, overexpression of PF4 accelerates tumor initiation and progression, with PLTs playing a significant mediating role." (PMID 40512151, 2025). "Pf4-expressing macrophages were recently described to promote tumor growth via TH1-Treg polarization." (PMID 40694429, 2025). "Exercise reduced cancer-induced splenomegaly decreasing platelet factor 4 mRNA levels in the CT26 tumor cells." (PMID 39555455, 2024). "IHC staining of human ccRCC tissues further confirmed the expression of PF4 in the tumor microenvironment." (PMID 38167034, 2024). "Activated platelets also release lysophosphatidic acid (LPA) and platelet factor 4 (PF4), which are crucial in the growth and invasion of tumor cells." (PMID 38348939, 2024). "On the other hand, by secreting thrombopoietic cytokines and tumour-derived platelet factor 4 (PF4), tumour cells induce thrombopoiesis." (PMID 36614896, 2022). "Second, PF4/CXCL4 (platelet factor 4) regulates tumor angiogenesis and inflammation within the tumor environment, and the other platelet-associated chemokines also have the same function, such as CTAP-III (connective tissue-activating peptide III)." (PMID 33997045, 2021). "Red blood cell counts and hemoglobin concentration were also slightly reduced in the tumor-bearing Dicer1fl/fl/Pf4-Cre mice." (PMID 34936674, 2021). "Platelet factor 4 (PF4) or CXCL4 is a protein that can inhibit tumor metastasis by decreasing blood vessel integrity, angiogenesis inhibition, increasing myeloid-derived suppressor cells (MDSCs), and hematopoietic stem cells (HSCs)." (PMID 34207884, 2021).